GPR152 (G protein-coupled receptor 152)
Description:
Orphan receptor.
Synonyms: PGR5
Tractability: Small molecule: it belongs to a druggable protein family. Antibody: UniProt places it where antibodies can reach, with medium confidence; UniProt predicts a signal peptide or a membrane-spanning region; its Gene Ontology location is reachable by antibodies, with medium confidence.
Target class: Family A G protein-coupled receptor; Membrane receptor
Gene: Protein-coding gene on chromosome 11 (67,451,301 to 67,452,729, reverse strand). Ensembl gene ENSG00000175514.
Subcellular location: Cell membrane
Gene Ontology:
Molecular function: identical protein binding; protein binding; G protein-coupled receptor activity
Biological process: G protein-coupled receptor signaling pathway
Cellular component: plasma membrane; membrane
Genetic constraint (gnomAD): Loss-of-function variants: 0 observed, 0.16 expected, observed/expected ratio (o/e) 0, 90% interval 0 to 1.88. That is too few expected variants to judge how well the gene tolerates losing a copy. Missense variants: 549 observed, 625.54 expected, observed/expected ratio (o/e) 0.88, 90% interval 0.82 to 0.94. Synonymous variants: 278 observed, 296.69 expected, observed/expected ratio (o/e) 0.94, 90% interval 0.85 to 1.03.
Homologues: Orthologues: chimpanzee GPR152 (99% identical), macaque GPR152 (94% identical), dog GPR152 (80% identical), pig GPR152 (80% identical), rat Gpr152 (78% identical), guinea pig GPR152 (77% identical), mouse Gpr152 (77% identical). Paralogues in human: MRGPRX2 (16% identical), MRGPRX1 (16% identical), MRGPRX4 (15% identical), MRGPRX3 (14% identical), MRGPRD (14% identical), MRGPRF (14% identical), MAS1 (14% identical), MRGPRG (14% identical), MRGPRE (13% identical), MAS1L (12% identical).